MTOR (mechanistic target of rapamycin kinase)
Diseases named in the same sentence as MTOR in open-access papers (continued):
Sharing a sentence is not in itself a finding about the gene and the disease.
cancer (continued). "The PI3K/AKT/mTOR pathway is thought to play a fundamental oncogenic role in cancers and is activated by the activating events in oncogenes PIK3CA, AKT1/2, and MTOR, or inactivating events in tumor suppressor genes such as PTEN, INPP4B, etc72." (PMID 34448553, 2021). "ATF4 depletion leads to the reduction of metastasis, cancer stemness, and tumor survival in vitro and in vivo and is involved in the TGFβ/SMAD and PI3K/mTOR pathways, playing growth factor-dependent functions." (PMID 33782384, 2021). "The PI3K/AKT pathway is also frequently altered in different cancer types, where disruptions in the function of phosphatidylinositol-3 kinases, AKT, or mTOR can result in increased or uncontrolled cell survival and growth." (PMID 34445194, 2021). "In KRAS mutant cancer cells, only inhibition of both the PI3K/AKT and MEK pathways resulted in complete inactivation of mTOR and increased cell death." (PMID 34830951, 2021). "In many cancers, including bronchial carcinoid, aberrations in the PI3K/Akt/mTOR survival pathway are the most common genomic abnormalities." (PMID 34316328, 2021). "Another important kinase sensor of the extracellular environment growth conditions is AMPK, which phosphorylates and activates TSC2 suppression of mTOR, and one clinically available AMPK inhibitor metformin has been repurposed for cancer treatments." (PMID 33668092, 2021). "We have studied the ability of NVP‐BEZ235 (PI3K/mTOR inhibitor) and AZD5363 (Akt inhibitor) in the sensitization of cancer cells to cisplatin and doxorubicin." (PMID 33338300, 2021). "At low concentration, NO includes in the activation and phosphorylation of ERKs, Akt/mTOR, STAT and Ras signal pathway to enhance angiogenesis and metastasis and stimulate cancer cell progression." (PMID 34356634, 2021). "In cancer cells, HIF is not only activated in oxygen shortages, but is also stimulated by other proteins, such as mTOR, which interacts with many receptors of tyrosine kinase, whose ligands are growth factors." (PMID 33916290, 2021). "These compounds inhibit cancer cell growth by targeting key growth signaling cascades such as tyrosine kinase receptor, Ras/MEK/ERK, and PI3-kinase Akt/mTOR pathways." (PMID 34639131, 2021). "AKT and mTOR are two classic cancer-promoting pathways and are regarded as downstream sites of PI3K/AKT/mTOR." (PMID 34819120, 2021). "One of the most commonly altered signalling pathways in cancer is the PI3K pathway, which converges in the activation of AKT and mTOR." (PMID 34968247, 2021). "In summary, the present review highlights the current understanding of D-2-HG in cancer biology, including reprogrammed metabolism, epigenome, redox balance, and signaling pathways, such as HIF and mTOR." (PMID 34571995, 2021). "In prior studies, we have shown that metformin causes a significant reduction in the conversion of OPLs into HNSCC in mice and that metformin decreases mTOR activity and HNSCC progression by acting on cancer-initiating cells directly." (PMID 34255745, 2021). "The literature suggests that the regulation of autophagy is complex, occurring via the Akt/mTOR and MAPK/Erk1/2 signaling pathways, and serves as a potential treatment against cancer." (PMID 33800788, 2021). "More importantly, the IGF-1/IGF-1R system mediates stimulatory effects in cancer cells via different routes such as the phosphatidylinositol-3kinasw(PI3K)/Akt1, mTOR, and MAPK." (PMID 35010954, 2021). "Utilizing mouse lung tissues in these experiments remains an open question about the validation of crosstalk between mTOR and Notch pathways in PASMC especially given the fact that Notch regulates mTORC1 in cancer cells." (PMID 33670032, 2021). "Jing and his colleagues reported that ERα in macrophages promotes the expression of chemokine (C–C motif) ligand 18 (CCL18) and accelerates the mTOR/KIF5B-induced EMT of endometrial cancer and cancer immune escape." (PMID 34098945, 2021).
cancer (continued). "Furthermore, elevated levels of PD-L1 expression following PTEN knockdown results in decreased proliferation and increased apoptosis in activated T cells and raise the possibility that targeting the PI3K/mTOR pathway as a therapeutic strategy may augment adaptive immune responses against cancer." (PMID 35250965, 2021). "Metformin exerts anti-cancer properties by activating the MAPK pathway, inhibiting the PI3K/AKT/mTOR pathway, increasing tumor suppressor genes, inducing G2/M cycle arrest, and various other processes." (PMID 34440224, 2021). "AKT activation leads to cell growth by activating mTOR through TSC1/2 phosphorylation, while increased levels of TSC1/TSC2 inhibit the mTOR pathway; mTOR positively regulates 4E-BP1 and p70S6k, which are activated in a variety of cancers." (PMID 33805447, 2021). "Currently, two drugs inhibiting the mTOR signaling pathway (Temserolimus and Everolimus) through the binding of FKBP-12 have been approved by the FDA (Food and Drug Administration) for cancer treatment (advanced renal cell carcinoma, tuberous sclerosis)." (PMID 34500781, 2021). "In cancer cells, the OXPHOS inhibition activates the LKB1–AMPK pathway, thus inhibiting the Raptor–mTOR complex (mammalian TOR complex 1 (mTORC1)) and the tuberous sclerosis complex 2 (TSC2)." (PMID 34439897, 2021). "Previous studies have found that endosomes are critical hubs in cancer cell signaling, including the AKT/mechanistic target of the rapamycin (mTOR) pathway." (PMID 34943938, 2021). "In cancer cells co-cultured with MSCs, the cell proliferation was increased, the Beclin expression and the LC3II/I protein ratio were decreased, and the mTOR expression was increased in MDA-MB 231 upon co-cultured with MSCs." (PMID 33643577, 2021). "The inability of compounds targeting the PI3K pathway to combat cancer growth and metastasis effectively, has only emphasised the fact of how extensive PI3K/AKT/mTOR signalling can be." (PMID 33810522, 2021). "PI3K/Akt/mTOR inhibition reduces SOX2 and OCT4 protein levels and thereby self-renewal and tumor-initiating capacity in some cancers." (PMID 33828530, 2021). "Several cancer signaling pathways (e.g. mTOR and RAS) have been shown to promote SG formation to enhance cancer cell survival, especially under stress." (PMID 34633481, 2021). "mTOR-dependent activation of the AMPK signalling pathway can control cell growth in all eukaryotes and is deregulated in most human cancers." (PMID 33752745, 2021). "PTEN is a tumor suppressor gene that is frequently inactivated in many cancers and normally functions as a negative regulator of the PI3K/Akt/mTOR signaling pathway (Sansal and Sellers, 2004)." (PMID 33987182, 2021). "On the other hand, combination therapies have been proposed for the inhibitors against mTOR/S6K1 and Hedgehog pathways together, as possibly more effective in cancer targeting." (PMID 34395258, 2021). "This is due to its ability to control mTOR activity and PI3K-AKT axis activity, which has been of great importance in cancer among other biological processes." (PMID 33412518, 2021). "In cancer immunity and brain metastasis, lncRNA Xist involves cancer immunity in high expression programmed cell death protein 1 ligand TNBC cells via activating both OCT4 and NANOG though activating PI3K/AKT/mTOR signaling pathway." (PMID 34178980, 2021). "As a negative regulator of PI3K/Akt/mTOR signaling, and having a tumor-suppressor role, the downregulation of PTEN expression can induce the malignant behavior of cancer cells." (PMID 33670518, 2021). "Hypoxia-related pathways including PI3K/AKT/mTOR, ERK, and the NF-ĸB are also involved in cancer cell proliferation and survival." (PMID 34639215, 2021). "Using The Cancer Proteome Atlas (TCPA), we therefore analyzed the protein expression of bona fide gene candidates related to mTOR and PI3K/Akt signaling, angiogenesis and immune signaling." (PMID 33791209, 2021).
cancer (continued). "Among the mechanisms frequently observed after the treatment of AR and its triterpenes in human cancer cells, the PI3K/Akt/mTOR pathway is likely to be the most frequently interrupted pathway." (PMID 34371964, 2021). "HDACs and HSP90 are involved in the activation of several oncogenic pathways in cancer maintenance, including the PI3K/AKT/mTOR, STAT, EGFR, and RAF/MEK/ERK pathways, which were also highly enriched in AML and ALL patient profiles." (PMID 33986242, 2021). "Growing numbers of natural compounds have been reported to modulate multiple signal pathways associated with autophagy, such as Ras-Raf-MEK-ERK, PI3K-Akt-mTOR and AMPK, thus exerting therapeutic effect on different cancers." (PMID 34512368, 2021). "PIK3CA and PTEN serve as central regulators of the PI3K/AKT/mTOR pathway and are known as bona fide HNSCC cancer genes." (PMID 35047999, 2021). "Collectively, our metabolic analyses implied that FATP5 loss augments glucose flux to support the glycolytic pathway and induce ATP production, inhibiting AMPK phosphorylation and activating mTOR signaling to promote EMT and cancer cell metastasis." (PMID 34772914, 2021). "Overexpressed in numerous human cancers, UBE2O targets AMPK for ubiquitination and degradation, which subsequently fosters the activation of the mTOR-HIF1a pathway." (PMID 34451875, 2021). "In other type of cancers, EZH2 has been shown to suppress several metabolic activities, including branched amino acid (BCAA) metabolism, TCA cycle (IDH1), mTOR (mammalian target of rapamycin) signaling, and glutamine metabolism." (PMID 35071240, 2021). "Then, the mechanistic experiments demonstrated that MEDAG regulated cancer progression and EMT through the AKT/AMPK/mTOR pathway." (PMID 33462219, 2021). "mTOR is known to be a major downstream target of AMPK signaling and has significant roles in cancer development." (PMID 33450887, 2021). "It has become increasingly clear that apart from its functions in cancer cells, the PI3K/AKT/mTOR pathway also regulates many processes within the TME." (PMID 35047999, 2021). "We further found that PcrV-mediated TAM reprogramming potentiated their NO-mediated cytotoxicity against cancer cells, effects that were exerted through the activation of a PI3K/AKT/mTOR-glycolysis-NO feedback loop via direct interaction with TLR4." (PMID 34900687, 2021). "GNB2 was involved in cancer initiation and progression by activating AKT/mTOR pathway, MAPK pathway, and Hippo signaling pathway." (PMID 35116059, 2021). "We found that AKT to GSK3 signaling is the most frequently observed relation, detectable in 30 cancer types, followed by other downstream proteins of AKT, including MTOR." (PMID 34179843, 2021). "Actually, NRAS is a very important gene involving many cancer-related signaling pathways, such as MAPK, mTOR, and PI3K-Akt signaling pathways." (PMID 33579226, 2021). "Several signaling pathways participate in cancer stem cell proliferation and survival, including the PI3K/Akt/mTOR pathway." (PMID 34831139, 2021). "However, because the reduction in HCC recurrence following the use of mTOR inhibitors has only been demonstrated in relatively small studies, high-quality studies, including well-designed multicenter studies, are needed to confirm the cancer preventive effects of mTOR inhibitors." (PMID 34638613, 2021). "The main target of AKT is the mammalian target of rapamycin (mTOR), which has a central role in the PI3K-AKT pathway and cancer disease." (PMID 34571969, 2021). "Mechanistically, Rh1-mediated ROS generation induced inhibition of the cancer cell survival signaling pathways, including PI3K/Akt/mTOR." (PMID 33920802, 2021). "Its significance in oncogenesis is highlighted by the plethora of inhibitors (dual PI3K–mTOR, PI3K, Akt and mTOR inhibitors) that are in clinical use or late-stage development for cancer treatment, with promising results in hematologic malignancies." (PMID 34948236, 2021).
cancer (continued). "We found that both curcumin and resveratrol were efficient in reducing cancer cell survival and that they differently affected autophagy, ROS and activation of the PI3K/AKT/mTOR pathway." (PMID 34832850, 2021). "Recently, it has been suggested that both HPV and EBV oncoproteins induce the initiation of EMT and the progression of human carcinomas through interactions with the JAK/STAT/SRC, β-catenin, PI3k/Akt/mTOR, and/or RAS/MEK/ERK signaling pathways." (PMID 34399719, 2021). "ERRα/PGC-1α/β activity is under the regulation of several oncogenic signals, including the PI3K/AKT/mTOR pathway which plays a key role in activating SREBP, a critical transcription factor involved in intracellular cholesterol synthesis in cancer cells." (PMID 32717915, 2020). "Some signaling pathways, such as HIF-1α, PI3K/mTOR and PPAR-γ, also up-regulate the expression of PKM2 to promote the growth of cancer cells." (PMID 32631382, 2020). "In further support of this possibility, melatonin is a known antiproliferative that normalizes several overactive pathways in both cancer and ADPKD, e.g., ERK, mTOR, PI3K/Akt, PKC." (PMID 33238462, 2020). "Some researchers believe that CA also reduces cancer cell viability through the inactivation of STAT3 signaling and AKT/mTOR pathway." (PMID 32352029, 2020). "Since METTL3 was reported to regulate mRNA translation in cancer cells, we decided to explore the role of METTL3 in the regulation of the PI3K/AKT/mTOR signalling pathway." (PMID 33090698, 2020). "Mammalian target of rapamycin (mTOR), is a key GBM oncogene that phosphorylates a wide variety of substrates involved in stress recovery and cancer pathogenesis." (PMID 33203845, 2020). "Typical dysregulated pathways in cancer include IGF-1R, PI3K/AKT1/mammalian target of rapamycin (mTOR), mitogen-activated protein kinase (MAPK)/ERK, glycogen synthase kinase-3β (GSK-3β), or Wnt/β-catenin signaling." (PMID 33520985, 2020). "Targeting dysregulated tumor driving pathways in human cancer has been a promising tool in cancer therapy and one such is the PI3K/AKT/mTOR signalling pathway." (PMID 33227065, 2020). "In this scenario, targeting PI3K/AKT/mTOR has become of high interest in the field of cancer and CRC, with a number of anti IGF-1 antibodies and tyrosine kinases or AKT/mTOR inhibitors being tested in numerous clinical trials." (PMID 31906264, 2020). "Beside, c-MYC and other transcription factors, such as mTOR and HIF-1, can act synergistically to improve glycolysis and promote cancer proliferation." (PMID 33489906, 2020). "Nevertheless, we can conclude that the appearance of escapers in the population of senescent cancer cells is associated with mTOR phosphorylation, however, without the transduction of signal to its substrate, which may be a cause of TFEB translocation to the nucleus." (PMID 32846959, 2020). "This confirms a mTOR/MMP axis reflecting the increased activation of the mTOR pathway in these cells, which has also been shown for several other cancers." (PMID 33287446, 2020). "Three miRNAs (miR-124-3p, miR-1-3p, and miR-24-3p) have been described as important factors associated with HCC tumorigenesis and function in established cancer-related pathways, including NOTCH, PI3K-Akt, and mTOR." (PMID 33424926, 2020). "Here we reviewed andrographolide on cellular pathways regulation including Wnt/β-catenin, mTOR, VEGF-mediated intracellular signaling, as well as TRAIL-mediated apoptosis to inhibit cancer development." (PMID 32759728, 2020). "As upstream of mTOR and MAPKs, epidermal growth factor receptor (EGFR) expression is inhibited by miRNA-7 to induce autophagic cell death in human cancer cells." (PMID 33239065, 2020).
cancer (continued). "As in cancer cells, PD-1 also regulates PI3K/AKT, MAPK/ERK1/2 and mammalian target of rapamycin (mTOR) pathways in T cells." (PMID 33014853, 2020). "KEGG pathway analysis revealed that DEGs in LUAD were related to many essential pathways in cancer pathogenesis, such as the MAPK pathway, ErbB pathway, calcium signaling pathway, Wnt pathway, and mTOR pathway." (PMID 32196072, 2020). "As such, GRB7 likely transmits signalling through PI3K/mTOR, MAPK, and RTKs, but also has a role in apoptosis, enabling cancer cells to proliferate and survive." (PMID 32737994, 2020). "The magnoflorine, a component of WJT, can ameliorate the strong pulmonary inflammation via suppressing NF-κB and MAPK activation, and it also induces the cancer cells apoptosis and autophagy through AKT/mTOR and p38 signaling pathways." (PMID 32518584, 2020). "The abnormal AKT/mammalian target of rapamycin (AKT/mTOR) pathway is one of the most common genomic abnormalities in BCs including TNBC3, contributing to cancer progression and resistance to existing treatments." (PMID 33311440, 2020). "In particular, mTOR inhibition induced insulin receptor substrate 1 (IRS-1) expression and abrogated feedback inhibition of the pathway, leading to Akt activation in cancer cell lines and in primary cell cultures." (PMID 32748870, 2020). "Such a metabolic pattern is reminiscent of the peculiar setup of the energy metabolism in cancer cells, i.e. Warburg effect, where a pivotal role is played by the PI3K/AKT–SGK1/mTOR signaling cascade." (PMID 32398164, 2020). "We previously reported TRIB2-mediated resistance to several anti-cancer agents, including the dual PI3K/mTOR inhibitor BEZ235." (PMID 33316942, 2020). "These proteins have also been shown to play key roles in cancer cells, influencing the AMPK/mTOR pathway and the TGF-β signaling pathway, and regulating apoptosis and cell proliferation." (PMID 32293333, 2020). "Given that mTOR signaling is frequently activated in many human cancers, DEPTOR usually acts as a tumor suppressor, by inhibiting mTOR, to suppress cell growth, and survival via inactivation of AKT5,6." (PMID 33184290, 2020). "There is considerable interest in small-molecule drugs targeting the PI3K/Akt/mTOR pathway, of which some have been approved by the United States Food and Drug Administration (FDA) for several human cancers." (PMID 32932888, 2020). "Studies have shown that pathways such as PI3K/AKT/mTOR and HIF-1α are central regulators of glycolysis, cancer metabolism, and cancer cell proliferation." (PMID 32076440, 2020). "In suppressing metastasis of cancer cells, apigenin administration interferes with the PI3K/Akt/mTOR signaling pathway as well as the expression of MMP-9, as a factor involved in the progression and invasion of cancer cells." (PMID 33195038, 2020). "We found co-occurrence of PI3K/Akt and mTOR pathway alteration in cancer and the PI3K/Akt and mTOR pathway were interconnected." (PMID 32863943, 2020). "We and others showed that TRIB2 confers resistance to several anti-cancer drugs, including PI3K/mTOR inhibitors, gemcitabine, dacarbazine and temozolomide." (PMID 33316942, 2020). "The anti-cancer effect of GJ/CDDP treatment is dependent on the induction of autophagy, in which process the AKT/mTOR pathway plays a crucial role." (PMID 31936835, 2020). "We are the first to indicate that the depletion of SAAL1 affected the characteristics of cancer aggressiveness and inhibited the HGF/Met-driven Akt/mTOR signaling pathway." (PMID 32650537, 2020). "In many cancer cells, overexpression of SESN2 contributes to inhibition of cell growth through AMPK phosphorylation, the mammalian target of rapamycin (mTOR) inhibition, and autophagy induction." (PMID 32155890, 2020). "As a therapeutic target for cancer, the PI3K/AKT/MTOR signalling pathway participates in regulating autophagy." (PMID 32200656, 2020).